LDHA (lactate dehydrogenase A)
Diseases named in the same sentence as LDHA in open-access papers (continued):
Sharing a sentence is not in itself a finding about the gene and the disease.
prostate carcinoma (56 papers, 2012 to 2025). A carcinoma that arises from epithelial cells of the prostate gland. "Elevated LDHA levels have been linked to poor prognosis in prostate cancer, with high LDHA and low LDHB levels associated with shorter survival and quicker recurrence." (PMID 40535811, 2025). "Assessed on prostate cancer cell lines LDHA has been validated as a biomarker of glycolysis-associated radio-resistance in cancer cells." (PMID 36568220, 2022). "Interestingly, it was demonstrated that high levels of phosphorylated LDHA in human prostate cancer tissues were associated with short recurrence and poor survival times in patients." (PMID 31737570, 2019). "In prostate cancer, pharmacological inhibition of LDHA with FX11 markedly suppresses lactate-driven tumor cell migration and angiogenesis." (PMID 41152975, 2025). "Elevated ACTN4 expression in prostate cancer upregulates LDHA expression, and other metabolic effects mediated by changes in ACTN4 expression have been suggested." (PMID 40980659, 2025). "Quantitative global succinylation profiling in prostate cancer revealed a significant increase in the succinylation of lysine 118 (K118su) of lactate dehydrogenase A (LDHA), enhancing LDH activity and exacerbating tumor progression." (PMID 39944690, 2025). "circARHGAP29 interacts with IGF2BP2 to improve lactate dehydrogenase A (LDHA) mRNA stability, thereby enhancing tumor cell glycolysis; the molecule provides a promising therapeutic target for docetaxel-resistant prostate cancer." (PMID 38778089, 2024). "Knockout of KDM4C suppresses glycolytic metabolism to inhibit prostate cancer metastasis by inhibiting C-Myc/LDHA signaling." (PMID 37117173, 2023). "A recent study has identified another post-translational mechanism of LDHA regulation via protein sirtuin 5 (SIRT5) in prostate cancer." (PMID 36551514, 2022). "Identifies LDHA as a possible target for overcoming resistance for Docetaxel in castration − resistant prostate cancer cells." (PMID 36568220, 2022). "LDHA is overexpressed in prostate cancer and induces a favorable microenvironment for tumor progression." (PMID 34463208, 2021). "In pancreatic and prostate cancer, a correlation of MYC with LDHA expression was detected and linked to the regulation of aerobic glycolysis while promoting tumor progression and decreasing apoptosis." (PMID 33925297, 2021). "Common targets down-regulated in NE-like prostate tumors included LDHA, already described in prostate cancer cells and activated by AR." (PMID 32041153, 2020). "LDHA expression levels have been previously correlated with prostate cancer progression, metastasis, and biochemical recurrence." (PMID 32110965, 2020). "These preclinical findings provide motivation for patient studies investigating drugs inhibiting LDHA activity alone or in combination with other prostate cancer treatments." (PMID 30813322, 2019). "In current study, we observed overexpression of LDHA in the clinical prostate cancer samples compared with benign prostate hyperplasia tissues as demonstrated by immunohistochemistry and real-time qPCR." (PMID 25983002, 2015). "Although without significant alternations in prostatic intraepithelial neoplasia, overexpressed LDHA was more commonly observed in prostate cancer." (PMID 25983002, 2015). "In PC-3 and LNCaP human prostate carcinoma cells, hypoxia dysregulates the expressions of lactate dehydrogenase A (LDHA), fatty acid synthase (FASN) and mitochondrial aconitase (mACON) genes." (PMID 25476483, 2015). "Moreover, there was no analysis of the clinical correlation between FOXD1 expression and glycolysis-related molecule levels (e.g., HK-2 and LDHA) in clinical prostate cancer samples, which weakens the clinical translational value of the study’s findings." (PMID 41214670, 2025).
prostate carcinoma (continued). "Previous studies in prostate cancer demonstrated that STAT1 could enhance tumor progression through transcriptional regulation of LDHA and LDHB, highlighting its significant role in metabolic regulation 32, underscoring its role in metabolic regulation." (PMID 41208879, 2025). "The clinical relevance of LDHA in prostate cancer was assessed." (PMID 35571619, 2022). "Consequently, Western blot results and luciferase assay consistently validated that miR-33b-5p effectively bond to 3′UTR region of LDHA to downregulate its expression in prostate cancer cells." (PMID 35571619, 2022). "Pearson's correlation coefficient analysis illustrated that lower miR-33b-5p expression was significantly associated with higher LDHA expression in PCa tumor specimens, suggesting that miR-33b-5p could target LDHA in prostate cancer." (PMID 35571619, 2022). "Furthermore, soluble adenylate cyclase (sAC) promotes the release of LDHA, accelerates cell proliferation, and induces the anti-irradiation effects in prostate cancer cells through the activation of BRAF/ERK1/2 signaling pathway." (PMID 29688867, 2018). "Taken together, our study revealed the oncogenic role of LDHA in prostate cancer and suggested that LDHA might be a potential therapeutic target." (PMID 25983002, 2015). "We proposed that inhibition of LDHA may represent a novel therapeutic strategy for controlling metastasis as well as tumor growth in prostate cancer." (PMID 25983002, 2015). "For example, lactate dehydrogenase A (LDHA) is desuccinylated at K118 by SIRT5, downregulates its activity and inhibits migration and invasion of prostate cancer (PCa) cells." (PMID 39979670, 2025). "A previous study has shown that under hypoxia conditions, HK2, LDHA, and glucose transporter 1 (GLUT1) are upregulated in prostate cancer cells, and brusatol treatment inhibits glycolysis by decreasing the expression of these glycolysis-related enzymes." (PMID 41214670, 2025). "In prostate cancer, FX11 treatment mitigates lactate-mediated angiogenesis and tumor cell migration, and similarly, FX11 inhibits LDHA-dependent cell proliferation, migration, and invasion in papillary thyroid carcinoma both in vitro and in vivo." (PMID 41152975, 2025). "Surprisingly, we found that GLDC correlates well with LDHA in gene and protein expression and regulates lactate levels through LDHA, strengthening the evidence that GLDC promotes glycolysis in prostate cancer." (PMID 37781511, 2023). "CircARHGAP29 increases LDHA stability by enhancing the interaction between LDHA and IGFBP2, leading to enhanced glycolytic metabolism in prostate cancer." (PMID 37819576, 2023). "LDHA has been identified as contributing to glycolysis in tumors, which strengthens the evidence that GLDC promotes glycolysis in prostate cancer." (PMID 37781511, 2023). "Melatonin-induced switch-off glycolytic function (decreased glucose uptake, and LDHA, MCT4 expression) has been partially described in prostate cancer and in Ewing sarcoma." (PMID 36359862, 2022). "According to our results, UBE2C highly expressed in prostate cancer, especially in castration-resistant prostate cancer and UBE2C was correlated with the neuroendocrine prostate cancer biomarkers, such as RB1 and LDHA." (PMID 33630978, 2021). "Aberrant activation of the FGFR1 signaling pathway is sufficient to enhance the Warburg effect through differential regulation of LDHA and LDHB in prostate cancer." (PMID 33390837, 2021). "FX-11, a specific inhibitor of LDHA, can promote the generation of DSBs and cell apoptosis by reducing the EMT, DNA repair capacity, hypoxia, and autophagy in prostate cancer cells, improving cell sensitivity to radiotherapy." (PMID 29688867, 2018). "Similarly, knockdown of phospholipase C-ε suppresses hypoxia-induced increase in the expression of HK2, LDHA, and GLUT1 in some types of prostate cancer cell lines." (PMID 41214670, 2025).
prostate carcinoma (continued). "LDHA-K118su, a SIRT5 substrate markedly elevates invasion and migration by prostate cancer cells." (PMID 37705968, 2023). "In prostate cancer, SIRT5 is responsible for increased lysine 118 desuccinylation of LDHA." (PMID 36551514, 2022). "Because succinylated Lys118 positively regulates LDHA enzymatic activity, it is not surprising that low SIRT5 expression was linked to prostate cancer progression." (PMID 36551514, 2022). "A similar effect of calcitriol has been found in LNCaP prostate cancer cells such that calcitriol transcriptionally downregulates various glucose metabolism-related genes, including SCL2A1 (GLUT1) and LDHA, and calcitriol also decreases glucose uptake and the expression of GLUT1." (PMID 34575112, 2021). "Moreover, lactate dehydrogenase A (LDHA), as a key enzyme in glycolysis, has been reported to have the biological function of promoting the Warburg effect and poor prognosis in many solid tumors, including prostate cancer 11-13." (PMID 37781511, 2023). "Furthermore, the depletion of CEMIP in prostate cancer cells reduces the expression of pyruvate dehydrogenase kinase isoform 4 (PDK4) and lactate dehydrogenase A (LDHA), enzymes important for efficient glycolysis in tumor cells, thereby decreasing cellular pyruvate, lactate, and ATP levels." (PMID 36291875, 2022). "However, the function of LDHA in prostate cancer has not been studied." (PMID 25983002, 2015).
hepatocellular carcinoma (49 papers, 2013 to 2026). A malignant tumor that arises from hepatocytes. "Studies have shown that LDHA is strongly associated with various human cancers, including pancreatic, head and neck, gastric, prostate, breast, hepatocellular carcinoma, and cervical cancer, etc51–54." (PMID 37853052, 2023). "Many studies had confirmed that the increased expression of HK2 and LDHA promoted the glycolysis process of tumor cells, thus accelerating the malignant phenotype of tumors, such as hepatocellular carcinoma and bladder cancer." (PMID 38218855, 2024). "It was shown that the overexpressed LDHA elevates the “stemness” properties of CSCs and enhances spheroid formation in hepatocellular carcinoma." (PMID 36230479, 2022). "For example, miR-142-3p suppresses aerobic glycolysis and hepatocellular cancer cell proliferation by targeting LDHA." (PMID 34336555, 2021). "A study revealed that the co-administration of DOX and apigenin dwindled the expression of hexokinase 2 (HK2) and lactate dehydrogenase A (LDHA) in the human hepatocellular carcinoma cell line, HepG2." (PMID 34715860, 2021). "Two of the most sensitive cell lines - HepG2 and Snu398 hepatocellular carcinoma cells - were selected for further investigation of the consequences of LDHA inhibition." (PMID 24280423, 2013). "LDHA inhibition resulted in profound changes in overall metabolism and survival in hepatocellular carcinoma cells." (PMID 24280423, 2013). "We found that inhibition of LDHA in hepatocellular carcinoma cells led to a rapid reduction of glucose uptake and lactate production." (PMID 24280423, 2013). "Upregulating LDHA leads to increasing lactate production and extracellular export, which in turn suppresses natural killer cell cytotoxicity and induces immune evasion, further promoting hepatocellular carcinoma development." (PMID 40940312, 2025). "LDHA plays an important role in metastasis and hepatocellular carcinoma cell growth." (PMID 35278714, 2023). "Knockdown of LDHA also restrained metastasis of hepatocellular carcinoma cells and tumor growth." (PMID 37398901, 2023). "A recent study on hepatocellular carcinoma cells has confirmed that APA-modified LDHA may directly participate in tumorigenesis by regulating the biological functions of microRNAs, validating the specific contribution of APA modification to LDHA." (PMID 32626751, 2020). "Knocking down LDHA enhances the cytochrome c release (the amount released is 5.38 ± 0.71 ng·mL−1 at 48 h LDHA shRNA Lenti treatment of hepatocellular carcinoma cells) from the mitochondria to the cytoplasm, providing a key signal initiating the irreversible death sequence." (PMID 31035592, 2019). "In addition, NDRG2 expression had an inverse association with LDHA expression and NDRG2 inhibited LDHA expression in hepatocellular carcinoma." (PMID 31523182, 2019). "Lei's research discovered significant upregulation of PRMT3 in hepatocellular carcinoma (HCC) and proved that PRMT3 facilitates glycolysis and HCC growth by enhancing arginine methylation of LDHA, serving as a potential biomarker for HCC patient prognosis." (PMID 39964832, 2025). "Our study aimed to elucidate the molecular mechanisms underlying NAC1 (nucleus accumbens associated 1) transcriptional regulation of LDHA and its role in HBV immune evasion, thus contributing to the development of cirrhosis and hepatocellular carcinoma (HCC)." (PMID 38704368, 2024). "In contrast, knockdown of LDHA significantly inhibited tumor growth and metastasis of hepatocellular carcinoma as well as the Warburg-like metabolic signature of mouse HCC." (PMID 36686771, 2022). "Similarly, Fang found that overexpression of miR‐383 could inhibit cell proliferation and invasion triggered by LDHA in hepatocellular cancer." (PMID 34668665, 2021). "Therefore, LDHA is a potential therapeutic target for hepatocellular carcinoma." (PMID 31523182, 2019).
hepatocellular carcinoma (continued). "• In hepatocellular carcinoma, SGC707 can inhibit the activity of PRMT3 and affect the methylation of LDHA by PRMT3; It can also block the enhancement of glycolysis induced by the overexpression of PRMT3." (PMID 41583428, 2025). "Circular RNA derived from the mitogen-activated protein kinase 9 (Circ_MAPK9) influences hepatocellular carcinoma progression through silencing miR-642b-3p, thereby promoting the STAT3 and LDHA expression." (PMID 38829380, 2025). "In hepatocellular carcinoma (HCC), H2B-K58 lactylation at the NDRG1 locus links the activity of LDHA to epigenetic control, creating a feedback loop that supports senescence-resistant clones." (PMID 41373440, 2025). "Similarly, LDHA was correlated with recurrence-free survival (RFS) in patients with hepatocellular carcinoma (HCC) in the GSE76427 database." (PMID 38993839, 2024). "In hepatocellular carcinoma cells, IRF5 upregulated the expression of lactate dehydrogenase A (LDHA) and promoted glycolysis, which can further contribute to the inflammatory environment." (PMID 39516356, 2024). "Wang and his colleagues discovered that lncRNA HULC binds directly to LDHA and PKM2, affecting their cellular localization, phosphorylation level, and enzyme activity, thereby promoting aerobic glycolysis in hepatoma cells." (PMID 37328616, 2023). "Inhibition of PDK4 and LDHA markedly suppresses CD133 (+) stemness characteristics and overcome resistance to sorafenib (current chemotherapeutic agent for hepatocellular cancer)." (PMID 26506419, 2015). "In contrast, hypoxia and HIF-1α induced expression of ENO1 and LDHA in another human cancer cell line, HEP3B hepatoma cells." (PMID 23866118, 2013). "In addition to HK2 and LDHA, some researchers discovered that NR3C2 inhibits cellular aerobic glycolysis by regulating PKLR, an isozyme of pyruvate kinase, in hepatocellular carcinoma cells." (PMID 36950803, 2023). "Their results showed that blocking Pyruvate Dehydrogenase Kinase 4 (PDK4) and Lactate dehydrogenase A (LDHA) significantly reduced CD133 + stemness features and helped patients overcome sorafenib resistance (chemotherapy medication currently used for hepatocellular cancer)." (PMID 36803831, 2023). "In hepatocellular carcinoma cells, LDHA is overexpressed due to downregulation of miR-383, triggering increased cell proliferation, invasion and glycolysis, MYC, NFκB, HIF-1α-mediated signaling enhances glycolysis in HCC by promoting upregulation of LDHA." (PMID 36686771, 2022). "In hepatocellular carcinoma (HCC), lactate accumulation induces H3K18la, which further upregulates SRSF10, indirectly increasing GLUT1, HK1, and LDHA expression, thereby sustaining lactate accumulation and histone lactylation." (PMID 40859309, 2025). "The miR-34a, which is also overexpressed in AITL, has a negative role in regulating glucose metabolism by lowering the expression of lactate dehydrogenase A (LDHA), whereas the downregulated miR-30b has a negative role in regulating lipid metabolism as reported in hepatocellular carcinoma." (PMID 37637043, 2023). "gluclncRNA (HULC) is up-regulated in hepatocellular carcinoma (HCC), directly binds LDHA, enhances the binding of LDHA to fibroblast growth factor receptor type 1 (FGFR1), thus promoting the glycolysis, proliferation, and progression of HCC cells." (PMID 34404767, 2021). "Knocking out of the YAP gene in human hepatocellular carcinoma (HCC) cell lines, HepG2, and MHCC97L cells, cultured in the stiff ECM, resulted in downregulation of glycolytic enzymes HK2 and LDHA, which subsequently reduced the migration capacity of cancer cells." (PMID 33718214, 2021). "Consistently, dual inhibition of LDHA, which blocks glycolysis end-step, and pyruvate dehydrogenase kinase 4 (PDK4), which favors the flow of pyruvate into the TCA cycle, represses the CSC phenotype in CD133+/PLC/PRF/5 hepatocellular carcinoma (HCC) cells." (PMID 33923958, 2021).